GINS2 (GINS complex subunit 2)
Diseases named in the same sentence as GINS2 in open-access papers (continued):
Sharing a sentence is not in itself a finding about the gene and the disease.
cancer (continued). "The results show that GINS2 overexpression is related to poor prognosis in some types of cancer." (PMID 36466552, 2022). "This is the first study on GINS2 as a prognostic and immune mechanism in pan-cancer." (PMID 36466552, 2022). "The expression of GINS2 is associated with MMR, MSI, TMB, and DNA methylation in various cancers." (PMID 36466552, 2022). "Based on our results, GINS2 can be used as a prognostic biomarker for some malignant tumours." (PMID 36466552, 2022). "As an oncogene, GINS2 can promote cell growth and inhibit cell apoptosis in various cancers." (PMID 36466552, 2022). "The expression of GINS2 is closely related to the expression of immune genes in various cancers." (PMID 36466552, 2022). "With regard to GINS2, it was reported that GINS2 could promote cancer cell proliferation, migration and invasion of non-small-cell lung cancer (NSCLC) via facilitating epithelial-to-mesenchymal transition and modulating PI3K/Akt and MEK/ERK signal pathway." (PMID 33648519, 2021). "Previous studies considered the potential effects of GINS2 on cancer progression." (PMID 33391406, 2021). "As it has been reported that DNA replication-associated proteins exhibit diverse functions in various cells, GINS components, particularly GINS2, have been suggested as possessing a function in cell division, and more precisely in the chromosome segregation of cancer cells." (PMID 24137407, 2013). "The high expression of GINS2 may promote the death of cancer patients." (PMID 36466552, 2022). "Therefore, we can understand the critical role of the GINS2 gene in cancers." (PMID 36466552, 2022). "GINS2 may be a valuable prognostic immunological biomarker of pan-cancer." (PMID 36466552, 2022). "The results showed that GINS2 might be a valuable prognostic immunological biomarker of pan-cancer." (PMID 36466552, 2022). "Also, the roles of GINS2 and EBNA1BP2 in PCa could be reflected by their associations with other cancers." (PMID 32953881, 2020). "The aberrant expression of other members of GINS (GINS1, GINS2, and GINS3) occurs in different types of human cancers." (PMID 37508549, 2023). "Interestingly, the expression of GINS2 is significantly correlated with multiple immune infiltration levels in human cancer, especially in LGG, LUSC, and TGCT, which indicates that GINS2 may mediate cancer progression by affecting immune infiltration in malignant tumours." (PMID 36466552, 2022). "GINS2, a member of the GINS family, plays a crucial role in DNA duplication and is highly expressed in various types of cancer." (PMID 34777484, 2021). "Searching for other proliferation genes resulted in finding EXO1, MCM10, GINS2, CDT1, ORC6L, and BLM had the same pattern indicating they are most likely necessarily highly transcribed in cancer." (PMID 31857847, 2019). "GINS2 is overexpressed in human EOC, promotes cancer progression and impairs apoptosis." (PMID 35810383, 2022). "Finally, both LINC00847 and CTD -2566J3.1 were co-expressed with essential genes for cancer genetic dependencies, such as FOXA1 y GINS2." (PMID 36359853, 2022). "Our cancer genetic dependency analysis found two essential genes with a DEMETER score ≤ −0.5 in the BT-474 cell line, which correspond to FOXA1 (DEMETER Score 0.83) and GINS2 (DEMETER Score 0.69)." (PMID 36359853, 2022). "Of all the cancer specimens examined, 29 (18.9%) were negative for GINS2, 93 (60.8%) were weakly positive for GINS2 expression, 25 (16.3%) were positive for GINS2 expression and 6 (3.9%) were strongly positive for GINS2 expression." (PMID 33391406, 2021). "Unfortunately, no comprehensive analysis on the role of GINS2 in pan-cancer has been reported." (PMID 36466552, 2022). "It is worth noting that in BLCA DLBC, PAAD, SARC, SARC STAD, and UCEC several kinds of cancer, GINS2 expression is positively related with TMB with MSI, suggesting that these types of cancer patients with high expression of GINS2 checkpoint inhibitors to vaccination may have a better response." (PMID 36466552, 2022).
GINS2 also shares sentences with these, for which no sentence is quoted: leukaemia (3 papers); lung squamous cell carcinoma (2); acute myeloid leukemia (1); chondrosarcoma (1); chronic myelogenous leukemia (1); clear cell renal carcinoma (1); colorectal cancer (1); COVID-19 (1); dengue (1); diffuse large B-cell lymphoma (1); Ewing sarcoma (1); fibrosarcoma (1); hereditary disease (1); Immunodeficiency (1); infection (1); intrahepatic cholangiocarcinoma (1); invasive breast carcinoma (1); large cell lung cancer (1); leiomyosarcoma (1); liver (1); Lyme disease (1); lymphoid neoplasm (1); malignant fibrous histiocytoma (1); Meier-Gorlin syndrome (1); microcephaly (1); microtia (1); myxofibrosarcoma (1); myxoid/round cell liposarcoma (1); ovarian serous cystadenocarcinoma (1); Pan (1).
A further 6 diseases each share a sentence with GINS2 in 1 paper.